CT47B1 (cancer/testis antigen family 47 member B1)
Synonyms: CT47.13; CT47A13
Tractability: No criterion of Open Targets' tractability assessment is met for any kind of drug.
Gene: Protein-coding gene on chromosome X (120,872,607 to 120,875,866, reverse strand). Ensembl gene ENSG00000236446.
Subcellular location (Human Protein Atlas): Nucleoli
Homologues: Orthologues: chimpanzee CT47B1 (94% identical), macaque CT47B1 (78% identical). Paralogues in human: CT47A1 (83% identical), CT47A10 (83% identical), CT47A11 (83% identical), CT47A12 (83% identical), CT47A2 (83% identical), CT47A3 (83% identical), CT47A4 (83% identical), CT47A5 (83% identical), CT47A6 (83% identical), CT47A7 (83% identical), CT47A8 (83% identical), CT47A9 (83% identical), and 1 more.